CABIN1 (calcineurin binding protein 1)
Description:
May be required for replication-independent chromatin assembly. May serve as a negative regulator of T-cell receptor (TCR) signaling via inhibition of calcineurin. Inhibition of activated calcineurin is dependent on both PKC and calcium signals.
Synonyms: CAIN; KIAA0330; PPP3IN; KB-318B8.7
Tractability: PROTAC: UniProt records ubiquitination sites on it; ubiquitination databases record sites on it; its protein half-life has been measured.
Gene: Protein-coding gene on chromosome 22 (24,011,192 to 24,178,634, forward strand). Ensembl gene ENSG00000099991.
Subcellular location: Nucleus
Subcellular location (Human Protein Atlas): Cytosol; Nucleoplasm
Pathways (Reactome):
Cellular responses to stimuli: Formation of Senescence-Associated Heterochromatin Foci (SAHF)
Gene Ontology:
Molecular function: protein binding; nucleosome binding; protein phosphatase inhibitor activity; transcription corepressor activity
Biological process: DNA replication-dependent chromatin assembly; cell surface receptor signaling pathway; chromatin organization; negative regulation of transcription by RNA polymerase II; nucleosome assembly; regulation of chromatin organization
Cellular component: HIR complex; nucleoplasm; nucleus
Genetic constraint (gnomAD): Loss-of-function variants: 130 observed, 227.62 expected, observed/expected ratio (o/e) 0.57, 90% interval 0.49 to 0.66. The upper end of that interval is the gene's LOEUF score, 0.66, which puts it in group 2 of 6, group 1 being the genes least tolerant of losing a copy. Missense variants: 2,404 observed, 2,933.7 expected, observed/expected ratio (o/e) 0.82, 90% interval 0.79 to 0.85. Synonymous variants: 1,086 observed, 1,189.2 expected, observed/expected ratio (o/e) 0.91, 90% interval 0.87 to 0.96.
Homologues: Orthologues: chimpanzee CABIN1 (99% identical), macaque CABIN1 (97% identical), dog CABIN1 (91% identical), rabbit CABIN1 (89% identical), mouse Cabin1 (89% identical), pig CABIN1 (88% identical), rat Cabin1 (88% identical), guinea pig CABIN1 (87% identical), tropical clawed frog cabin1 (65% identical), zebrafish cabin1 (55% identical), zebrafish si:ch73-313l22.2 (7% identical).
Diseases named in the same sentence as CABIN1 in open-access papers:
CABIN1 is named in the same sentence as 16 diseases in open-access papers, as found by Europe PMC text mining. Sharing a sentence is not in itself a finding about the gene and the disease. The quoted sentences say what the papers report.
adenoma (1 paper, 2009). A neoplasm arising from the epithelium. "Except for NR2F2 (p<0.954), all genes were differentially expressed not only between the three subclasses of adenomas (t-test, p<0.05), but also between the four groups of follicular tumors (F-tests, p<0.05 for ADAMTS2, CABIN1, ALDH13, USP13; p = 0.06 for KRTHB5)." (PMID 19893615, 2009).
diabetes (1 paper, 2020). "In addition, we identified nine genes (CABIN1, CKS1B, C19orf60, SDR39U1, SLC31A1, DNAJA4, ZC3H8, OTUD3 and UBALD1) not previously associated with diabetes, but that are known to be involved in processes potentially linked to β-cell dysfunction, such as cell turnover, oxidative stress and ER stress." (PMID 33575641, 2020).
gastric cancer (1 paper, 2022). A primary or metastatic malignant neoplasm involving the stomach. "Furthermore, a 153 cfDNA methylation biomarker panel including DOCK10, CABIN1, and KCNQ5 was identified in a GC patient cohort, providing a novel method to diagnose early-stage gastric cancer." (PMID 36302755, 2022).
herpesvirus infection (1 paper, 2019). "Recent studies have shown that the HIRA (histone cell cycle regulator) histone H3.3 chaperone complex, composed of HIRA, Ubinuclein 1 (UBN1), and Calcineurin-binding protein 1 (CABIN1), relocalizes to PML-NBs in response to replication-defective herpesvirus infection." (PMID 30901352, 2019).
Hypertension (1 paper, 2019). The presence of chronic increased pressure in the systemic arterial system. "CABIN1 which was detected using Het-meta-Q2 and Het-meta-Q3 (p value = 8.67e-06 and 6.91e-06 respectively) is known to be associated hypertension arterial and purpura thrombotic thrombocytopenic that is closely related blood pressure." (PMID 31296221, 2019).
lymphoma (1 paper, 2021). A malignant (clonal) proliferation of B- lymphocytes or T- lymphocytes which involves the lymph nodes, bone marrow and/or extranodal sites. "Finally, while CABIN1 was previously reported to be mutated in only 4% of DLBCL samples, an unbiased CRISPR screen of six lymphoma cell lines found it to be an essential gene with tumor suppressor behavior." (PMID 35528192, 2021).
MALT lymphoma (1 paper, 2021). An indolent, extranodal type of non-Hodgkin lymphoma composed of small B-lymphocytes (centrocyte-like cells). "Overall, our data show that CABIN1 is expressed in MALT lymphomas and that CABIN1 CN losses/mutations cause a decrease in the expression of CABIN1 in some OAMZL." (PMID 35528192, 2021). "OAMZL cases expressed CABIN1 less frequently than MALT lymphomas originating in other anatomic locations, the latter uniformly expressing CABIN1 (P = 0.0009)." (PMID 35528192, 2021). "Next, we used IHC to assess CABIN1 protein level in our cohort of OAMZL (29 specimens with available tissue) and other MALT lymphomas (35 samples)." (PMID 35528192, 2021).
scrapie (1 paper, 2022). A fatal disease of the nervous system in sheep and goats, characterized by pruritus, debility, and locomotor incoordination. "Of all the selected genes, significant changes between the control and scrapie animals were found in the expression of five genes: PCDH19, SNCG, WDR45B, PEX1, and CABIN1." (PMID 35252421, 2022). "We identified many DMRs between the control and scrapie animals, some of them belonging to genes with possible neuroprotective roles against neurodegeneration (SNCG and WDR45B) and to genes that may facilitate or contribute to scrapie disease progression (PCDH19, PEX1, and CABIN1)." (PMID 35252421, 2022).
tumor (3 papers, 2017 to 2024). "In OAMZL samples, CABIN1 was affected by missense mutations in 9 different tumor samples, two of which were configured as somatic events that occurred in samples with paired normal tissue." (PMID 35528192, 2021). "The A6053G mutant affecting PEST domain exhibited increased protein stability in cycloheximide chase assay compared with WT protein and had CABIN1 expression in the tumor like OAMZL tumors with WT CABIN1 based on IHC." (PMID 35528192, 2021). "In our experiments, we confirmed that deletion of CABIN1 enhances BCR-induced NFAT reporter activity, gene expression, and is associated with constitutive presence of NFATc1 in the nucleus of the primary OAMZL tumor cells." (PMID 35528192, 2021).
CABIN1 also shares sentences with these, for which no sentence is quoted: cancer (2 papers); colorectal cancer (1); meningioma (1); neurological diseases (1); osteosarcoma (1); purpura (1); schwannomatosis (1).